ROR1 (ROR family WNT receptor 1)
Diseases named in the same sentence as ROR1 in open-access papers (continued):
Sharing a sentence is not in itself a finding about the gene and the disease.
leukemia (continued). "Co-cultures of leukemia-associated Wilm’s tumor protein 1 (WT1) and tyrosine-protein kinase transmembrane receptor 1 (ROR1)-reactive CTLs and of CD123-redirected switchable CAR T cells were prepared in the presence of MSCs and assessed for cytotoxic potential, cytokine secretion, and expansion." (PMID 38231344, 2024). "Collectively, these studies indicate that expression of ROR1 and ROR1-signaling may reduce the sensitivity of leukemia cells to venetoclax, potentially helping to contribute to venetoclax resistance." (PMID 35418613, 2022). "Surface ROR1 was also analyzed in MCL cells from peripheral blood of leukemia patients (n = 11)." (PMID 36297673, 2022). "The increased expression of BCL2L1 induced by Wnt5a-activation of ROR1 may account in part for the enhanced resistance to venetoclax of leukemia cells that express high levels of ROR1." (PMID 35418613, 2022). "Moreover, the combination of venetoclax with cirmtuzumab—ADC-7 was tested and showed a valuable synergistic effect in targeting ROR1-positive leukemia and lymphoma cell lines." (PMID 33445713, 2021). "In addition, truncated ROR1 which lost the extracellular matrix and transmembrane regions was detected in central nervous system, leukemias and a variety of human cancers." (PMID 34763666, 2021). "In more recent studies on CLL cells, we described that Wnt5a could induce ROR1 to recruit and activate guanine exchange factors (GEFs), and thereby enhance leukemia-cell migration and proliferation." (PMID 30568170, 2019). "Consistent with this concept are studies demonstrating that high-level leukemia-cell expression of ROR1 can enhance disease progression in mouse models, and associate with a shorter median time from diagnosis to initial therapy and shorter survival for patients with CLL." (PMID 30568170, 2019). "Recently, ROR1 expression was reported to elevate in human leukemia and a variety of solid malignancies, suggesting that ROR1 may serve as a potential target for cancer therapy." (PMID 28427197, 2017). "Thus, such CAR+ T cells with long-lived potential could migrate to secondary lymphoid structures harboring ROR1+ leukemias." (PMID 26030772, 2015). "The leukemia cells of TCL1-Tg mice lack ROR1, whereas the leukemia cells of ROR1xTCL1 dTg mice express human ROR1 at levels comparable to that of ROR1Pos CLL." (PMID 40295829, 2025). "We focused on highly expressed antigens found in primary leukemia and lymphomas, such as CD19, CD20, CD22, ROR-1, CD276, CD79B, and CD10." (PMID 36289682, 2022). "Collectively, these results indicate that expression of ROR1 was sufficient to enhance expression of NF-κB target genes, including BCL2L1, in MEC1 leukemia cells." (PMID 35418613, 2022). "In summary, we found that Wnt5a induces ROR1 to recruit and activate DOCK2, leading to activation of ERK1/2, which appears responsible for the capacity of Wnt5a to enhance leukemia-cell proliferation." (PMID 33097837, 2021). "Collectively, these studies reveal that Wnt5a induces ROR1 to complex with cortactin/HS1/ARHGEF1 at P841, which induces phosphorylation of cortactin and HS1, activation of ARHGEF1 and RhoA, thereby enhancing leukemia-cell migration." (PMID 30568170, 2019). "Wnt5a, a ligand for ROR1 and ROR2, induced ROR1/ROR2 hetero-oligomerization and enhanced leukemia chemotaxis and proliferation." (PMID 29856777, 2018). "Wnt5a, a ligand of ROR1, induces ROR1/ROR2 heterooligomerization to enhance leukemia chemotaxis and proliferation." (PMID 27830754, 2016). "We also examined for differences in MMP-9 expression by leukemia cells with or without ROR1 in murine leukemia models." (PMID 40295829, 2025). "In leukemia B cells, we found that Wnt5a could upregulate MMP-9 expression via ROR1-dependent activation of NF-κB." (PMID 40295829, 2025). "This allowed us to monitor the transduction efficiency of each lentivirus vector for MEC1 cells, a human leukemia cell line lacking endogenous ROR1." (PMID 39062146, 2024).
leukemia (continued). "Using flow cytometry (FC) with a AF647-labelled Hu4-2-17-LC clone, we analyzed whole blood and frozen samples from CLL and HCL cases to confirm previously published ROR1 prevalence, adding more information to the infrequent HCL type that accounts for 2% of all leukaemias." (PMID 39495778, 2024). "In this study, we examined the leukemia-cell expression of ROR1 and ROR1-signaling of patients who failed to clear MRD after more than a year of therapy with venetoclax." (PMID 35418613, 2022). "Here we report our studies evaluating whether cortactin is recruited to ROR1 upon stimulation with Wnt5a, undergoes tyrosine phosphorylation, and recruits/activates ARHGEF1 to promote F-actin polymerization and leukemia-cell migration." (PMID 30568170, 2019). "Receptor-tyrosine-kinase-like orphan receptor 1 (ROR1) is expressed during embryogenesis and by certain leukemias, but not by normal adult tissues." (PMID 22403610, 2012). "For instance, we could not address the mechanism of Wnt5a-mediated ROR1/2 hetero-dimerization in regulation of downstream signaling, which was previously shown to modulate leukemia chemotaxis and proliferation." (PMID 35504983, 2022). "Recent studies have demonstrated that Wnt5a could induce activation of Rac1 in leukemia cells of patients with CLL via a ROR1-dependent pathway, which could not be inhibited by ibrutinib." (PMID 29872501, 2018). "Some patients treated with vaccines of autologous leukemia cells genetically engineered to promote anti-leukemia immune responses generated auto-antibodies specific for Ror1 that did not react with non-tumor tissues showing that this receptor is specific to cancer cells." (PMID 28432357, 2017). "Receptor tyrosine kinase-like orphan receptor 1 (ROR1) represents a promising target antigen, because it is expressed on leukemia and lymphoma cells but not on healthy tissues." (PMID 35158894, 2022). "Prior studies using the leukemia cell-line, MEC1, found that these cells expressed Wnt5a, but not ROR1." (PMID 33097837, 2021). "Because the lymphocytes of healthy adults do not express ROR1, this pathway of Wnt5a-induced DOCK2 phosphorylation may be restricted to leukemia B cells." (PMID 33097837, 2021).
mantle cell lymphoma (39 papers, 2011 to 2025). Mantle cell lymphoma is a rare form of malignant non-Hodgkin lymphoma affecting B lymphocytes in the lymph nodes in a region called the ``mantle zone''. "The encouraging results obtained from JeKo‐1 cells led us to analyze the proapoptotic mechanism of the most effective synthesized derivatives, confirming that ROR1 inhibition promoted cell death in mantle cell lymphoma." (PMID 40328670, 2025). "A novel antibody-drug conjugate, zilovertamab vedotin, targets ROR1 and has shown activity in mantle cell lymphoma and CLL." (PMID 40943662, 2025). "ROR1, a cell surface protein, is expressed in various malignancies, such as mantle cell lymphoma (MCL), acute lymphoblastic leukemia (ALL), and specific types of lung, ovarian, colon, breast, pancreatic, and renal cancers." (PMID 37779899, 2023). "In another study, NFκB p65 was identified as a downstream target of Wnt5a/ROR1, leading to drug resistance in mantle cell lymphoma (MCL)." (PMID 32751131, 2020). "Specifically for NHLs, when compared to PBMCs, ROR1 mRNA and/or protein are elevated in all or a subset of primary samples of mantle cell lymphoma (MCL), marginal zone lymphoma (MZL), diffuse large B-cell lymphoma (DLBCL), and follicular lymphoma." (PMID 24752542, 2014). "Subsequently, it was found that ROR1 is also expressed in certain other B-cell malignancies, such as mantle cell lymphoma and marginal zone lymphoma." (PMID 23285131, 2012). "Mantle cell lymphoma (MCL) is B cell malignancy that also expresses ROR1." (PMID 29872501, 2018). "ROR1 has also been shown to be overexpressed in several other hematological malignancies, including mantle cell lymphoma (MCL), as well as in solid tumors." (PMID 36297673, 2022). "ROR1 is also aberrantly expressed in mantle cell lymphoma (MCL), triggering pro-survival signals similar to those in CLL and B-ALL." (PMID 34123850, 2021). "Based on its selective cell surface expression in chronic lymphocytic leukemia (CLL) and mantle cell lymphoma (MCL), receptor tyrosine kinase ROR1 has recently emerged as a promising target for therapeutic monoclonal antibodies (mAbs)." (PMID 21698301, 2011). "Flow cytometry results indicated that the MDA-MB-231 (triple-negative breast cancer, TNBC), Jeko-1 (mantle cell lymphoma), and PC3 (prostate cancer) cell lines were ROR1-positive." (PMID 39816690, 2025). "In chronic lymphocytic leukemia (CLL) and mantle cell lymphoma (MCL), for example, the majority of patient samples show aberrant expression of receptor tyrosine kinase-like orphan receptor 1 (ROR1), a receptor of beta-catenin-independent Wnt signaling." (PMID 36561363, 2022). "Further, expression of ROR1 is highly upregulated in chronic lymphocytic leukemia (CLL), acute lymphoblastic leukemia (ALL) and mantle cell lymphoma (MCL)." (PMID 25029443, 2014). "Although we previously demonstrated that cell surface ROR1 can mediate the internalization of pAbs and mAbs in primary CLL cells and mantle cell lymphoma cell lines, it was important to confirm this in the setting of pediatric ALL." (PMID 23285131, 2012). "In addition to WNTs, ROR1 has been shown to form a functional complex with CD19 at the cell surface, particularly in the context of mantle cell lymphoma (MCL), leading to the activation of signaling pathways that promote MCL cell proliferation." (PMID 40869147, 2025). "Preclinical studies suggest that ROR-1 targeted therapies like the use of CAR T and BiTEs, could be effective in treating CLL and Mantle cell lymphoma (MCL) (NCT04763083)." (PMID 39551787, 2024). "Consistent with this notion is the recent study in a related ROR1-expressing hematologic malignancy, namely mantle cell lymphoma (MCL), that showed that silencing ROR1 could repress activation of ERK1/2 in MCL cells." (PMID 33097837, 2021).
mantle cell lymphoma (continued). "In hematological diseases, the strong expression of ROR1 has been described in CLL and mantle cell lymphoma (MCL), while moderate and heterogeneous expression has been noted in marginal zone lymphoma, DLBCL, and follicular lymphoma." (PMID 38927948, 2024). "Furthermore, the anti-ROR1 blocking antibody cirmtuzumab has shown efficacy in chronic lymphocytic leukemia (CLL) and mantle cell lymphoma (MCL) trials." (PMID 35204808, 2022). "A similar expression pattern of ROR1 and other non-canonical Wnt pathway components is observed in mantle cell lymphoma (MCL)." (PMID 33261128, 2020). "ROR1 is not a unique marker for CLL, but is also highly prevalent in other non-Hodgkin lymphoma (NHL) entities, especially in mantle cell lymphoma (MCL)." (PMID 33445713, 2021).
lung cancer (32 papers, 2015 to 2025). A malignant neoplasm involving the lung. "In lung cancer, ROR1 is involved in the activation of c-Src and MET, causing inhibition of tumor cell apoptosis." (PMID 34123850, 2021). "The present study investigated the association of the AKT/mTOR signaling pathway with ROR1 silencing against erlotinib resistance in lung cancer." (PMID 31452776, 2019). "Similarly, Heabah and colleagues observed an association of ROR1 expression in lung carcinoma with a positive lymph nodal status." (PMID 41355329, 2025). "Indeed, targeting ROR1 helped to reinstall sensitivity to erlotinib treatment in resistant lung cancer cell lines, thus further underlining its potential as a therapeutic target." (PMID 33445713, 2021). "Furthermore, higher expression of ROR1 is associated with more aggressive and poorer prognosis in breast, ovarian and lung cancers, in which ROR1 regulates expression of genes involved in epithelial-mesenchymal transition (EMT)." (PMID 28427197, 2017). "Lung cancer cells were co-cultured with either unmodified T cells or ROR1 CAR-T cells for 24 h at the ratio of 1:1." (PMID 39849645, 2025). "A preclinical study showed that administration of oxaliplatin and cyclophosphamide enhances chemokine expression and accumulation of CAR-T cells in a mouse model of ROR1+ lung cancer." (PMID 38727261, 2024). "CAR-T cells directed against the receptor tyrosine kinase-like orphan receptor 1 (ROR1) showed a strong anti-tumor activity in human lung cancer A549 cell lines." (PMID 36831396, 2023). "In another study, ROR1 CAR-T cells have been found to be effective in inducing apoptosis of 3D lung cancer tumors in static culture." (PMID 37420216, 2023). "In both breast and lung cancer, ROR1-targeted CAR-T cells significantly restricted tumor growth and prolonged tumor survival." (PMID 35911706, 2022). "ROR1 CAR T-cells can effectively kill lung cancer cells in a three-dimensional tumor model of NSCLC." (PMID 36497465, 2022). "ROR1, a tyrosine kinase-like orphan receptor, is upregulated in both lung cancer and breast cancer but has very low expression in normal tissues." (PMID 35911706, 2022). "A phase I clinical trial of ROR1 CAR-T cells was conducted in patients with refractory ROR1+ lung cancer, TNBC, and hematologic malignancies (NCT02706392)." (PMID 34332618, 2021). "Treatment with receptor tyrosine kinase-like orphan receptor 1-specific (ROR1)-CAR T cells supports strong antitumor activity in human lung cancer A549 cell lines." (PMID 33494834, 2021). "This fits to the report discussed earlier that, in lung cancer cells, targeting ROR1 can help to circumvent resistance due to its role in sustaining signaling of several pro-survival RTKs." (PMID 33445713, 2021). "More systematic investigations are required to validate the precise role of ROR1 in lung cancer cells." (PMID 34123850, 2021). "ROR1 was also found at high levels in lung cancer cells, which serves as a prognostic biomarker in patients with lung adenocarcinoma." (PMID 34123850, 2021). "Alternatively, in lung cancer cells ROR1 was shown to be important for sustaining the EGFR-ERBB3-mediated activation of PI3K, revealing another potential regulatory crosslink." (PMID 33445713, 2021). "Previous studies have demonstrated that ROR1 is an oncogene that is highly expressed in numerous types of hematologic malignancy and several types of solid tumor, including lung cancer." (PMID 31452776, 2019). "Our RNA results mirror similar results for ROR1 in IHC with elevated levels in pancreatic, ovarian, and lung cancers." (PMID 31137681, 2019). "There were some reports about ROR1 expression in lung cancer, but most data were based on cellular and animal experiments." (PMID 27830754, 2016). "In lung cancer cell lines, ROR1 sustains a favorable balance between pro-survival PI3K-AKT and pro-apoptotic p38 signaling, and knockdown of ROR1 induces apoptosis in cancer cells." (PMID 27830754, 2016).
lung cancer (continued). "A high level of ROR1 expression was noted to be associated with an aggressive and poor prognosis disease in, for example, CLL, DLBCL, MCL, ALL, as well as in ovarian, breast, pancreatic, gastric, colorectal, and lung cancers." (PMID 37111634, 2023). "However, aberrant expression of ROR1 has been observed in several haematological malignancies and solid tumours including breast, ovarian and lung cancers." (PMID 34763666, 2021). "Blockade of ROR1 in lung cancer cells was found to suppress expression of CDK4 and CCNE1, two important cell cycle regulators, as well as Bcl-XL and Bcl-2, two critical anti-apoptotic factors, while it increased the expression of several pro-apoptotic factors including Bak, caspase-3, and caspase-7." (PMID 33445713, 2021). "They demonstrated that ROR1 knockdown inhibited lung AC cell lines, proposing that this receptor could represent a valuable therapeutic target in lung cancer patients." (PMID 33172431, 2020). "Indeed, LEF1 and ROR1 are expressed by a variety of human cancers including melanoma, colorectal cancer, pancreatic cancer and lung cancer." (PMID 26050196, 2015). "A series of antigens targeting surface proteins, including EGFR, CEA, MSLN, HER2, ROR1, MUC1, and DLL3 in lung carcinoma cells have been incorporated into CAR structure to allow CAR-T cells target lung cancer tissue." (PMID 40624569, 2025). "ROR1 has also been shown to form heterodimers with EGFR, promoting the maintenance of lung cancer cell survival." (PMID 37111634, 2023). "Current antigen targets in clinical trials for CAR-T cell therapy for lung cancer include MUC-1, CEA, HER2, mesothelin, receptor tyrosine kinase-like orphan receptor 1 (ROR1), glypican-3 (GPC3), EGFR, and PD-1." (PMID 37420216, 2023). "Meanwhile, in the lung cancer NCI-H1975 model, the mice received 2 × 106 cells of Mock-T or ROR1 Hinge CAR-T-cells." (PMID 35892876, 2022). "Both ROR1 and ROR2 were found to be highly expressed in a lung cancer cell line derived from CTCs from a patient with relapsed small cell lung cancer." (PMID 33445713, 2021). "In a previous study, receptor tyrosine kinase-like orphan receptor 1 (ROR1) bound to EGFR led to activation of the phosphatidylinositol 3 kinase (PI3K) pathway, which is critical in lung cancer." (PMID 26945426, 2016). "Data indicate that replicating cells might be vulnerable to cell death at exposure to the ROR1 inhibitor KAN0441571C and/or that KAN0441571C induced a cytostatic effect in lung cancer cells preventing exit from G2/M phase and cell proliferation." (PMID 37111634, 2023). "ROR1 expression was significantly higher in non-squamous (136/157, 86%) and squamous (60/106, 57%) lung cancer patients compared to 5/24 (21%) patients with neuroendocrine tumors (p = 0.0001)." (PMID 37111634, 2023). "Since it was identified as a transcriptional target of homeobox protein Nkx-2.1, a major lineage-survival oncogene in lung cancer, it is not surprising that many lung tumors harbor ROR1." (PMID 33445713, 2021). "Furthermore, ROR1 has been identified as a transcriptional target of homeobox protein NKX-2, which is required for sustained EGFR signaling in lung cancer patients and serves as an independent prognostic predictor of OS." (PMID 34319035, 2021). "ROR1 expression is independent of classical lung cancer molecular alterations and not correlated, in a Caucasian cohort, to TTF-1 expression." (PMID 33172431, 2020). "ROR1 regulates the expression of the genes involved in epithelial-mesenchymal transition as well as sustains a favorable survival balance between the pro-survival PI3K-AKT and the pro-apoptotic p38 signaling in lung cancer." (PMID 29856777, 2018). "ROR1-mediated signaling pathways in lung cancer are not fully understood." (PMID 31452776, 2019). "As expected, KAN0441571C induced dephosphorylation of ROR1 in a dose-dependent manner, as well as EGFR, SRC, PI3K110δ/AKT/mTOR (non-canonical Wnt pathway), and CREB in the NCI-H23 lung cancer cell line." (PMID 37111634, 2023).